SCD (stearoyl-CoA desaturase)
Diseases named in the same sentence as SCD in open-access papers (continued):
Sharing a sentence is not in itself a finding about the gene and the disease.
glioblastoma (continued). "Inhibition of SCD also results in a decrease in MUFA and an accumulation of SFA in glioblastoma cells, leading to ER stress and apoptosis of glioblastoma cancer cells through activation of inositol-requiring enzyme 1 (IRE1) and c-Jun N-terminal kinase (JNK) mitogen-activated protein kinase (MAPK)." (PMID 37046844, 2023). "Isolated cell lines from glioblastoma tumors have diverse SCD expression, some lines showing no detectable SCD expression, and others with high expression." (PMID 37046844, 2023). "According to the GEPIA database, the level of SCD expression in glioblastoma tumors does not affect patient prognosis, which may indicate a limited role of this enzyme in the tumorigenesis of glioblastoma." (PMID 37046844, 2023). "However, it appears that reduced SCD expression in glioblastoma tumors does not affect the composition of fatty acids in the tumor." (PMID 37046844, 2023). "Thus, we performed GC-MS based analysis of the total fatty acid in eight human glioblastoma tumors and found that, overall, GBM tumors have nearly equivalent relative SCD activity (palmitoleate to palmitate ratio) and FADS2 activity (sapienate to palmitate ratio)." (PMID 36338708, 2022).
lung adenocarcinoma (21 papers, 2010 to 2024). A carcinoma that arises from the lung and is characterized by the presence of malignant glandular epithelial cells. "Collectively, our data indicate that increased level of SCD is associated with aggressiveness and poor prognosis of lung adenocarcinoma." (PMID 36514170, 2022). "Taken together, our study illustrates that high level of OA in CAF-supernatant is transferred to lung adenocarcinoma cells via lipid transporter and reprograms the lipid metabolism by upregulated SCD under glucose-deficient conditions." (PMID 36514170, 2022). "Our data indicated that SCD expression was negatively correlated with survival rate in patients with lung adenocarcinomas." (PMID 36514170, 2022). "Analysis of tumor tissue microarray from lung adenocarcinoma patients revealed that SCD expression was the marker for poor prognosis involving tumor grade, clinical stage and survival rate." (PMID 36514170, 2022). "The Cancer Genome Atlas (TCGA) data revealed that the lung adenocarcinoma patients with high SCD expression had lower survival rate than the patients with low SCD expression." (PMID 36514170, 2022). "The expression of SCD was examined immunochemically in human adenocarcinoma tissues, and its clinical relevance to survival rate in lung adenocarcinoma patients was assessed by Kaplan–Meier analysis." (PMID 36514170, 2022). "Overexpression of Fatty Acid Synthase (FASN) correlates with poor prognoses and treatment resistance in NSCLC, and stearoyl CoA desaturase 1 (SCD1) is highly expressed in lung adenocarcinomas promoting in vitro and in vivo tumorigenesis, cell migration and invasion." (PMID 36439419, 2022). "Expression of F-actin is significantly suppressed by SCD-inhibitor in lung adenocarcinoma." (PMID 36514170, 2022). "Indeed, the percentage of SCD positive cells was increased with the grade and stage in lung adenocarcinoma tissues." (PMID 36514170, 2022).
pancreatic cancer (21 papers, 2017 to 2025). "In a pancreatic cancer model, increased availability of extracellular palmitate induces lipotoxic cell death and curbs tumor growth while SCD overexpression considerably increases it." (PMID 36338708, 2022). "We also compared the expression of LXRβ and known target genes SREBF1, ABCA1, ABCG1, FASN, and SCD in pancreatic cancer tissue to normal pancreas tissue and found that transcript levels of LXRβ and its target genes are elevated in the tumor tissues." (PMID 33348693, 2020). "High levels of SCD have been described to increase cell proliferation and survival in pancreatic tumors, and its inhibition has been shown to brake tumor growth in lung, colorectal, osteosarcoma and breast tumors." (PMID 30913248, 2019). "In addition, the NR4A1 ligand DIM-4-OH downregulates expression of stearoyl-CoA-desaturase in pancreatic cancer cells to activate ferroptosis however, in this study expression of the desaturase was minimal in TNBC cells." (PMID 40313760, 2025). "In addition, the NR4A1 ligand DIM-4-OH downregulates expression of stearoyl-CoA-desaturase in pancreatic cancer cells to activate ferroptosis." (PMID 41184246, 2025). "Interestingly, inhibition of CLU and SCD has been previously shown to suppress proliferation of pancreatic cancer cells and pancreatic tumor growth." (PMID 37978383, 2023). "By suppressing Nur77 in pancreatic cancer cells, FBW7 (F-box and WD repeat domain-containing 7) reduces the expression of stearoyl-CoA desaturase (SCD1) and enhances ferroptosis." (PMID 38789431, 2024).
non-alcoholic fatty liver disease (20 papers, 2013 to 2026). "Deletion of Asah2 alleviates diet-induced nonalcoholic steatohepatitis/nonalcoholic fatty liver disease via downregulation of stearoyl-CoA desaturase (Scd1) and reduces cholesterol accumulation." (PMID 37944753, 2023).
bladder cancer (19 papers, 2017 to 2025). "High levels of SCD mRNA and protein have been associated with poor prognosis in patients with bladder cancer." (PMID 37240297, 2023). "In one study, SCD expression in bladder cancer patients was found to be significantly associated with poor prognosis." (PMID 34869576, 2021). "Next, we were not able to explore the exact mechanism that underlies the biological function of SCD in bladder carcinoma." (PMID 30592142, 2019). "Supporting this, public datasets show that inhibition or knockout of PPARG in bladder carcinoma cells significantly reduces SCD expression." (PMID 41383134, 2025). "Analysis of the TCGA database revealed a significant positive correlation between FADS2 expression in bladder cancer and the activity markers SCD and FASN, which reflect SREBP activity." (PMID 40682485, 2025). "Bladder cancer tissues from three different patients (#1, #2, and #3) exhibited markedly higher levels of SCD, SUMF2, and KDEL2R compared to the corresponding paracancerous tissues." (PMID 39104534, 2024). "Experimental evidence shows that targeting SCD with siRNA significantly reduces the proliferation and migration of bladder cancer cells, further confirming its role in cancer progression." (PMID 39107713, 2024). "Inhibition of SCD activity was capable of decreasing the migration and invasion abilities of bladder cancer cell lines." (PMID 37240297, 2023). "Research has revealed that SCD is highly expressed in pancreatic and bladder cancers, and protects cancer cells from ferroptosis." (PMID 36247434, 2022). "In summary, SCD inhibition was capable of decreasing the migration and invasion abilities of bladder cancer cell lines in vitro." (PMID 30592142, 2019). "In our study, we elaborated for the first time on the relationship between SCD gene activity and bladder cancer." (PMID 30592142, 2019). "To verify the potential biological functions of SCD in bladder cancer, we performed several cancer‐related assays." (PMID 30592142, 2019). "A significant correlation between SCD gene expression and poor prognosis among patients with bladder cancer was observed in our data." (PMID 30592142, 2019). "Likewise, SCD is highly expressed in the CSC subpopulation of human bladder cancer, while silencing of SCD reduces CSC formation and mitigates cisplatin resistance." (PMID 36514170, 2022). "We obtained the results of immunohistochemical staining of ACOT13, CYP1, DECR1, IL4I1, and SCD in both normal tissues and bladder cancer tissues and found that the expression of CYP1 was higher in normal tissues, while other genes were higher in tumor tissues than in normal tissues." (PMID 36131793, 2022). "All data indicated that SCD directly regulates bladder cancer cell growth." (PMID 30592142, 2019). "To examine whether the SCD gene could affect the cellular function of bladder cancer cells, we inhibited SCD activity using two SCD‐specific siRNAs and the SCD‐specific inhibitor A939572." (PMID 30592142, 2019). "Thus, we conclude that high SCD expression indicates poor prognosis in patients with bladder urothelial cancer, and the blockade of SCD gene activity significantly inhibits the proliferation and invasion of bladder cancer cells." (PMID 30592142, 2019). "Therefore, we selected a target gene, stearoyl CoA desaturase‐1 (SCD), among the differentially expressed genes (DEGs) between BCSCs and their parental bladder cancer cells." (PMID 30592142, 2019). "However, SCD inhibitors may target CSCs specifically to suppress proliferation and evoke apoptosis in CSCs in patients with bladder cancer." (PMID 30592142, 2019). "Besides, the abundance of SCD is much more higher than PI3 in bladder cancer." (PMID 30592142, 2019). "Bioinformatics analysis of bladder cancer transcriptome data from the TCGA database revealed a significant positive correlation between FADS2 expression and SCD and FASN, molecules that reflect SREBP activity." (PMID 40682485, 2025).
bladder cancer (continued). "In cisplatin-resistant bladder cancer cell lines, FLRT2, HOXC5, SCD, GRM7, HMGA1, ETV7, and SCO2 were highly expressed, while EMP1, SERPINA6, and ZNF124 exhibited lower expression levels." (PMID 39744172, 2025). "Immunohistochemical staining revealed that SCD, SUMF2, and KDEL2R were significantly more expressed in bladder cancer tissues compared to paracancerous tissues, while TM4SF1 exhibited higher expression in paracancerous tissues than in tumor tissues." (PMID 39104534, 2024). "The Lee bladder dataset is considered because it contains gene expression levels for both SCD and PI3, survival status, follow‐up time, TNM stage and progression status for patients with bladder cancer." (PMID 30592142, 2019). "Moreover, the results of differential relative expression of hub genes, SCD, DDR2, and MT1A, in bladder cancer cells compared to normal urothelial cells from RT-qPCR experiments were consistent with those of DEA on transcriptomic data from the TCGA cohort." (PMID 39107713, 2024). "Unlike many other types of cancer, the inhibition of SCD may not increase the efficacy of conventional chemotherapy in bladder cancer." (PMID 30592142, 2019).
glioma (19 papers, 2017 to 2024). A benign or malignant brain and spinal cord tumor that arises from glial cells (astrocytes, oligodendrocytes, ependymal cells). "SCD was found to be one of the several hypermethylated genes in Glioma-CpG island methylator phenotype (G-CIMP) characteristic of proneural tumors." (PMID 33568479, 2021). "In another study, the increased expression of SCD in T98G and U87 MG glioma cells correlated with higher temozolomide (TMZ)-resistance, which contributed to the reduced survival of patients after TMZ-based chemotherapy." (PMID 32392704, 2020). "We found that FASD1 may be a key gene for the joint action of AMD and COVID-19, and SCD regulates the immune infiltration of macrophages in glioma and germ line tumors." (PMID 38625951, 2024). "It was also shown that CD133+ glioma stem cells from in vitro cultured neurospheres display elevated FADS1 and FADS2 activities and that SCD and FADS2 exhibit spatial heterogeneity with higher expression in the peritumoral area." (PMID 36338708, 2022). "There are no data that would link higher SCD expression to negative prognoses for glioma patients." (PMID 32392704, 2020).
hypertriglyceridemia (19 papers, 2009 to 2026). A laboratory test result indicating elevated triglyceride concentration in the blood. "Furthermore, hypertriglyceridemia was correlated with an increase in SCD-1 activity and decrease in plasma n-3 PUFA in an ethnic-specific manner." (PMID 20565855, 2010).
liver fibrosis (19 papers, 2020 to 2025). "The inverse association between TAG 18:1n-9 and liver fibrosis could be considered contradictory, however, it might reflect an enhanced desaturation and elimination of lipotoxic 16:0 through enhanced SCD-1 activity." (PMID 35083257, 2021). "As confirmed, MUFAs produced by stearoyl-CoA desaturase provided a Wnt-positive signaling loop via stabilization of low-density lipoprotein-receptor-related proteins 5 and 6, which contributed to liver fibrosis and tumor growth." (PMID 35008393, 2022). "Furthermore, SCD mRNA expression was significantly upregulated in hepatic stellate cells (HSCs) that activate the Wnt-pathway by stabilizing the Frizzled/low-density lipoprotein (LDL) receptor-related protein (LRP) 5/6, promoting liver fibrosis." (PMID 39682753, 2024).
clear cell renal cell carcinoma (17 papers, 2013 to 2024). "The combination of SCD inhibitor A939572 with Tisirolimus synergistically inhibits the growth of clear cell renal cell carcinoma both in vitro and in vivo." (PMID 39351232, 2024). "Numerous studies have shown that A939572 is a potent SCD1 inhibitor, and many preclinical studies have used A939572 as a control (Stearoyl-CoA desaturase 1 is a novel molecular therapeutic target for clear cell renal cell carcinoma." (PMID 37777801, 2023). "Stearoyl-CoA desaturase 1 (SCD1), the rate-limiting enzymes in the biosynthesis of monounsaturated fatty acids from saturated fatty acids, have been gradually recognized as a potential therapeutic target for various malignancies, particularly in clear-cell renal cell carcinoma (ccRCC)." (PMID 27861513, 2016). "Furthermore, SCD1, the main isoform of SCD in humans, is induced by hypoxia in clear cell renal carcinoma cells and regulates the expression of HIF2α through a positive feedback loop involving Akt." (PMID 24203995, 2013).
lipid metabolism disorders (16 papers, 2018 to 2025). "In order to study the influence of SCD on lipid metabolism disorder in CC cells, lipid metabolism indicators were tested." (PMID 38355626, 2024). "It has been reported that SREBP-1, SCD-1, and FASN are involved in the regulation of lipid synthesis, and their abnormal expression can lead to lipid metabolism disorders." (PMID 37297416, 2023). "Previous studies have shown that HNK can alleviate lipid metabolism disorders of NASH by suppressing the expression of SREBP-1c, FAS, SCD-1 and promoting the phosphorylation of ACC, which are the key genes involved in fatty acid and unsaturated fatty acid biosynthesis pathways." (PMID 37709801, 2023).
non-small cell lung carcinoma (15 papers, 2017 to 2025). A group of at least three distinct histological types of lung cancer, including non-small cell squamous cell carcinoma, adenocarcinoma, and large cell carcinoma. "Similarly, the accumulation of LD and overexpression of stearoyl-CoA desaturase 1 (SCD1) were observed in non-small cell lung cancer (NSCLC) cells resistant to EGFR-tyrosine kinase inhibitors (TKIs)." (PMID 37841917, 2023). "Inhibiting SCD could result in tumor cell death including anaplastic thyroid carcinoma, colorectal adenocarcinoma, renal cell carcinoma, and non-small cell lung carcinoma." (PMID 34721037, 2021). "EGFR-TKI-resistant non-small-cell lung carcinoma (NSCLC) cell lines are characterized by an accumulation of LD and overexpression of Stearoyl-CoA Desaturase 1 (SCD-1), a key enzyme converting saturated fatty acids into unsaturated fatty acids." (PMID 39886047, 2025).
Alzheimer disease (11 papers, 2011 to 2025). A progressive, neurodegenerative disease characterized by loss of function and death of nerve cells in several areas of the brain leading to loss of cognitive function such as memory and language. "Studies have shown that SCD inhibitors play a beneficial role by reducing the oleic acid concentration in animal models of Parkinson's disease, Alzheimer's disease, and demyelinating disorders." (PMID 37974120, 2023). "SCD has been reported to be upregulated together with MUFAs in Alzheimer’s disease (AD)." (PMID 40459948, 2025). "Besides, the dysregulation of the enzyme stearyl coenzyme A desaturase-I (SCD-1), which is responsible for oleic synthesis within the central nervous system, has been shown to act as a possible driving force to the Alzheimer’s disease pathology." (PMID 33498506, 2021). "In this review we describe how its ability to inhibit stearoyl-CoA desaturase (SCD) directly, can be of interest as a coadjuvant for the treatment for various diseases, such as, nonalcoholic steatohepatitis, Alzheimer’s disease, cancer, and retinal disorders." (PMID 31936134, 2020). "Thus, levels of MUFAs in hippocampus, frontal cortex and temporal cortex were elevated in Alzheimer’s disease patients, as was the expression of the SCD isomers SCD1, SCD5a, and SCD5b." (PMID 24058332, 2013).
Hyperglycemia (10 papers, 2013 to 2026). An increased concentration of glucose in the blood. "We found that ATP citrate lyase (ACLY), acetyl-Co-A carboxylase (ACACA) which converts acetyl-CoA into malonyl-CoA, fatty acid synthase (FASN) and acetyl-CoA desaturase (SCD) were increased in normoglycemia in MIC26 KOs but mostly unchanged in hyperglycemia." (PMID 39393820, 2024). "Several carbohydrate metabolism genes involved in metabolism of monosaccharide and carbohydrate and hyperglycemia (e.g. CPT1A, GALK1, INS, LEPR, PRLR and SCD) are highly expressed in mouse CPE and only lowly in human CPE." (PMID 24391755, 2013). "However, the sustained reduction in hyperglycemia after the cessation of OA treatment is clearly independent of the lipogenic pathway in the liver because the effects on SREBP-1c, ACC, FAS and SCD-1 have all subsided." (PMID 25222566, 2014).
Parkinson disease (10 papers, 2020 to 2025). A progressive degenerative disorder of the central nervous system characterized by loss of dopamine producing neurons in the substantia nigra and the presence of Lewy bodies in the substantia nigra and locus coeruleus. "SCD inhibition ameliorates neuronal toxicity caused by aberrant α-synuclein, a lipid-binding protein implicated in Parkinson’s disease." (PMID 35060064, 2022). "Stearoyl-CoA desaturase (SCD) is a potential therapeutic target for Parkinson’s and related neurodegenerative diseases." (PMID 35060064, 2022). "Mechanistically SCD inhibition was shown to inhibit α-synuclein-induced lipid accumulation, toxicity, and neuronal degeneration in Parkinson’s disease models." (PMID 35443751, 2022). "Based on our unbiased discovery of SCD inhibitors in yeast and their protection against α-synuclein toxicity in neurons, we established a drug discovery program to identify novel potent, brain-penetrant SCD inhibitors for the treatment of Parkinson’s disease." (PMID 35060064, 2022). "Recent in vivo validation of SCD as a target for Parkinson’s disease was obtained in a mouse model of α-synuclein toxicity." (PMID 35060064, 2022). "Here, we report the independent discovery and validation of stearoyl-CoA desaturase (SCD) as a modulator of α-synuclein (αSyn)-induced pathology and toxicity in cell-based Parkinson’s disease (PD) models." (PMID 34301719, 2021). "In addition, the low expression of SCD and high expression of MTF1 were associated with systemic lupus erythematosus, parkinsons disease, and pathogenic escherichia coliinfection." (PMID 37904700, 2023). "Taken together, extensive in vitro and in vivo analyses support the further evaluation of YTX-7739 as an SCD inhibitor for the treatment of Parkinson’s disease and provides evidence for key relationships among α-synuclein, lipid biology, and stearoyl-CoA desaturase." (PMID 35060064, 2022). "In Parkinson's disease, increases in monounsaturated fatty acids (MUFA) in phospholipid membranes promote α‐synuclein binding, aggregation, and toxicity, and the inhibition of stearoyl‐CoA desaturase (SCD), the enzyme responsible for synthesizing MUFA, alleviates α‐synuclein toxicity." (PMID 40406919, 2025).